VEGFA (vascular endothelial growth factor A)
Diseases named in the same sentence as VEGFA in open-access papers (continued):
Sharing a sentence is not in itself a finding about the gene and the disease.
diabetic retinopathy (continued). "In addition, oxidative stress suppressed the expression of miR-205-5p in retinal epithelial ARPE-19 cells; thus, VEGFA expression and angiogenesis increased, which may be a potential mechanism of diabetic retinopathy." (PMID 34370714, 2021). "Similarly, here we also found YY1 could upregulate VEGFA and Snail1 expression to regulate diabetic retinopathy development." (PMID 34267179, 2021). "Vascular endothelial growth factor-A (VEGF-A) induces vascular hyperpermeability in specific tissues and in various pathological conditions, including diabetic retinopathy and ischemic disorders." (PMID 38052807, 2023). "High levels of Yap1 expressed in the retinas of mice with diabetic retinopathy upregulate MALAT1 and target VEGFA by regulating miR-200b-3p." (PMID 36035997, 2022). "For instance, VEGF release, particularly the isoform VEGFA, in combination with reactive oxygen species (ROS) production in diabetic retinopathy has been shown to enhance retinal degeneration, whereas VEGFD is protective for RGCs and the retinal vasculature." (PMID 35629305, 2022). "VEGFA, AKT1, and IL-6 were recognized as core targets in the network pharmacology prediction study of Astragalus membranaceus in treating the diabetic retinopathy, and the PI3K-Akt signaling pathway role has also been highlighted." (PMID 35607520, 2022). "One example of such complexity in translational control is the Vascular Endothelial Growth Factor A (VEGF-A) protein, which is upregulated in many diseases such as cancers, arthritis, diabetic retinopathy and psoriasis." (PMID 22708490, 2012). "Yet, anti-VEGF agents are not entirely protective in all patients with diabetic retinopathy and there are safety concerns for retinopathy of prematurity including reduced circulating VEGFA levels leading to neurocognitive decline and pulmonary hypertension." (PMID 39934776, 2025). "MMDHP may be effective for the treatment of diabetic retinopathy through active ingredients luteolin, acacetin, naringenin, and alisol B via AKT1, SRC, and VEGFA in AGE-RAGE, PI3K-AKT, and Rap1 signaling pathways." (PMID 36467890, 2022). "Furthermore, emodin can also impact diabetic retinopathy and cataract through inhibition of retinal neovascularization via modulation of HIF-1α/VEGF signaling pathway and through decreasing expressions of VEGFA, HIF-1α, and PHD-2." (PMID 34589130, 2021). "VEGFA is the most important cytokine that induces angiogenesis and neovascularization, and neutralization of VEGFA is a primary treatment for neovascular AMD and diabetic retinopathy (DR) patients; but it is also a known neuroprotective cytokine." (PMID 32234075, 2020). "Besides, the VEGF signaling pathway played an important role in the diabetic retinopathy involved in multiple targets including PIK3CG, PTGS2, and VEGFA." (PMID 29051733, 2017). "Metformin does not disrupt VEGFA by downregulating the expression of the gene but rather by influencing its alternative splicing and the production of nonprotein coding isoforms of the gene in a model for diabetic retinopathy." (PMID 36287120, 2022). "In summary, the results of the present study demonstrate that Mingmu Dihuang pill may be effective for the clinical treatment of diabetic retinopathy through active ingredients luteolin, acacetin, naringenin, and alisol B via AKT1, SRC, and VEGFA in AGE-RAGE, PI3K-AKT, and Rap1 signaling pathways." (PMID 36467890, 2022). "Among the factors involved in diabetic retinopathy (DR), nerve growth factor (NGF) and vascular endothelial growth factor A (VEGFA) have been shown to affect both neuronal survival and vascular function, suggesting that their crosstalk might influence DR outcomes." (PMID 36291113, 2022).
diabetic retinopathy (continued). "Due to the significant role played by vascular endothelial growth factor A (VEGF) in endothelial cell dysfunction, intravitreal injection (IVI) of its neutralizing antibody has been widely used to treat diabetic macular edema (DME) and proliferative diabetic retinopathy (PDR) in clinical practice." (PMID 31943789, 2020). "However, it has been suggested that in diabetic retinopathy certain metalloproteinases involved in regulation of the extracellular matrix and vascular basement membrane thickening are inhibited by AAT, resulting in reduced VEGFA levels and potentially vasculopathy." (PMID 39934776, 2025). "In a similar manner, Yi and co-workers showed that the total expression of VEGFA was not reduced by Metformin treatment, following STZ-induced diabetic retinopathy." (PMID 33062917, 2020).
ovarian carcinoma (816 papers, 1997 to 2026). A malignant neoplasm originating from the surface ovarian epithelium. "VEGFA is also upregulated in many tumors, and its expression is associated with tumor development, including ovarian carcinomas, and is a target in many cancer therapies under development." (PMID 38255198, 2024). "Among the genes that were highly expressed and commonly significant LR pairs in both the R and NR groups, CD74, GAS6, and VEGFA were associated with carcinogenesis and were prominent markers of targeted therapy in ovarian cancer." (PMID 39135097, 2024). "Kaplan–Meier survival analysis spotlighted AKT1, JUN, EGFR, and VEGFA as potential diagnostic and prognostic biomarkers for ovarian cancer." (PMID 37964873, 2023). "Vascular Endothelial Growth Factor A, encoded by VEGFA, was found to be overexpressed in many cancers including ovarian cancer." (PMID 34439877, 2021). "VEGFA (vascular endothelial growth factor A) is known as another target gene of miR-205 increasing the ovarian cancer risk by targeting EMT progression factors." (PMID 34721577, 2021). "The similar results in a previous research proved that miR-205 was implicated in the progression of ovarian cancer via targeting VEGFA, and was able to inhibit the invasion of ovarian cancer cells." (PMID 31719795, 2019). "VEGFA-mediated permeability causes oedema with severe consequences for both progression and treatment of brain tumours, ovarian carcinomas, stroke complications and diabetic macular oedema." (PMID 30006556, 2018). "Vascular endothelial growth factor A (VEGF-A) is known to contribute to endothelial cell proliferation, including tumor-induced angiogenesis, and has been associated to VM in ovarian carcinoma and melanoma." (PMID 28320399, 2017). "Recent work has implicated VEGFA as a driver of malignant stem‐like cells in certain cancers, but the relevance to ovarian cancer and the downstream pathways through which VEGFA‐driven stem cell expansion were not known." (PMID 28179359, 2017). "Elevated levels of VEGFA are associated with increased formation of new blood vessels in tumor tissue, and have become an important factor contributing towards improved accuracy of ovarian cancer diagnosis." (PMID 40836974, 2024). "CircASH2L and VEGFA levels were positively associated with each other in ovarian cancer tissues." (PMID 37234708, 2023). "In addition, the currently available studies also confirm that in ovarian cancer, VEGFA expression is associated with the development of chemoresistance of cancer cells and induction of autophagy." (PMID 36012171, 2022). "However, the biological mechanisms of anti-ovarian cancer effects of mogroside V associated with VEGFA remain unreported." (PMID 35464051, 2022). "Besides, VEGFA expression level in ovarian cancer tissues was positively associated with circRhoC expression (P = .000)." (PMID 31639291, 2019). "Finally, overall survival analysis of a cohort of ovarian cancer patients (n = 1435) indicates that high levels of VEGFA, AKT1 and SRC-α and low miR-765 expression were associated with worst patients outcome." (PMID 31157166, 2019). "VEGFA have been also implicated in ovarian cancer prognosis." (PMID 29855486, 2018). "Exosomes from donor ovarian cancer cell SKOV3 shuttled miR-205 could affect the proliferation, migration, invasion, apoptosis and EMT progression of receptor SKOV3 cells via regulating VEGFA, making miR-205 to be a potential diagnostic biomarker of ovarian cancer." (PMID 31719795, 2019). "A true positive prediction involved combining mirvetuximab soravtansine (anti-FOLR1 + tubulin inhibitor) with bevacizumab (anti-VEGFA) in platinum-resistant ovarian cancer." (PMID 41149468, 2025). "As a downregulated miRNA in ovarian cancer tissues, miR-126 ectopic expression decreases tumor proliferation, invasion, and angiogenesis in vitro via targeting VEGFA and tumor growth in vivo." (PMID 39967908, 2025).
ovarian carcinoma (continued). "MiRNAs, small non-coding RNAs involved in regulating post-transcriptional gene expression, have been found to influence ovarian cancer development by regulating vascular endothelial growth factor A (VEGFA) gene expression." (PMID 39857448, 2025). "Loss of FLNB inhibits vascular permeability and, in ovarian cancer cells, promotes MMP9-mediated tumour invasion and VEGFA-mediated angiogenesis plus induces tumour growth." (PMID 41373535, 2025). "DHA substantially inhibited CSC properties, tumorigenicity and vascular endothelial growth factor A (VEGF-A)-mediated tumor neovascularization in ovarian cancer." (PMID 41345229, 2025). "In ovarian cancer, the upregulation of AKT1 and VEGFA is associated with proliferation, metastasis, and angiogenesis." (PMID 38666020, 2024). "Studies have confirmed that high levels of VEGFA are related to poor prognosis in tumors such as in gastric cancer, ovarian cancer, HCC, non-small cell lung cancer, and endometrial cancer." (PMID 38532022, 2024). "Previous studies reported that AKT1 and VEGFA have key roles to play in the pathogenesis of ovarian cancer." (PMID 38666020, 2024). "Inhibition of AKT1 and VEGFA signaling has been shown to reduce ovarian cancer cell proliferation, angiogenesis, and tumor growth in preclinical models." (PMID 38666020, 2024). "In our research, VEGF signals were significantly enriched in ovarian cancer and VEGFA was significantly expressed in EC-1-Cancer cells." (PMID 37124501, 2023). "Louis, MO, USA) inhibited the mRNA expression of VEGF isoforms (VEGFA-VEGFD) in ovarian cancer cell lines (ES-2 and OV-90 cells)." (PMID 37233501, 2023). "Meanwhile, VEGFA also takes part in the process of ovarian cancer and follicle development by modulating the progression of angiogenesis, autophagy, and apoptosis." (PMID 38037065, 2023). "Second, by searching the literature, we found VEGFA and PIK3R1 protein are the most interconnected among our selected cancer type risk factors, including Endometrial cancer, Ovarian cancer, Cervical cancer and Thyroid cancer." (PMID 36608061, 2023). "Among these targets, part of these genes has been referenced for pathophysiology functions in ovarian cancer, such as VEGFA." (PMID 37831733, 2023). "Previous research showed that VEGFA produced by ovarian cancer cells stimulates MDSC migration and differentiation through VEGFR1 expression in MDSCs." (PMID 37046797, 2023). "It has been demonstrated that VEGFA isoforms positively correlated with tumor biology and were co-expressed in ovarian cancer as indicators of tumor activity." (PMID 36230822, 2022). "This potential interplay of Notch3 along with p21 and VEGFA evidently emerges as critical regulators during tumor metastasis leading to the progression of ovarian carcinoma." (PMID 35884426, 2022). "MiR-205 is involved in the proliferation, migration, invasion and apoptosis of ovarian cancer cells by regulating the target gene VEGFA." (PMID 36439168, 2022). "The first immunological drug used in ovarian cancer was bevacizumab (a recombinant humanized monoclonal antibody blocking angiogenesis by inhibiting VEGF-A (vascular endothelial growth factor A)." (PMID 35054356, 2022). "VEGFA, a core protein docked well with mogroside V, has been identified as a pharmacological target in mogroside V treatment of ovarian cancer and COVID-19." (PMID 35464051, 2022). "Upregulation of VEGFA plays an important role in the oncogenesis and progression of ovarian carcinoma." (PMID 36230822, 2022). "Recently, in primary ovarian carcinoma culture, VEGFA had been shown to promote tumor-initiating cells through Src-DNMT3A-driven miR-128-2 methylation and Bmi1 upregulation." (PMID 35884426, 2022). "In the context of proliferation, ovarian cancer cells release exosomal miR-205 that promotes cell proliferation and invasion by targeting vascular endothelial growth factor A." (PMID 36439168, 2022).
ovarian carcinoma (continued). "Treatment of fibroblasts with exosomes from ovarian cancer cells changed the expression of the VEGFA gene (Vascular endothelial growth factor A)." (PMID 36012171, 2022). "Anti-VEGFA therapy in ovarian cancer has already been confirmed to improve the effectiveness of standard treatment." (PMID 36230822, 2022). "The randomized phase II AVANOVA trial compared niraparib plus the Vascular Endothelial Growth Factor-A (VEGF-A) inhibitor bevacizumab to niraparib alone in platinum-sensitive recurrent ovarian cancer patients." (PMID 35205700, 2022). "VEGFA expression and its activation of VEGFRs were correlated to metastasis, tumor angiogenesis, and chemotherapy resistance in ovarian cancer." (PMID 34439877, 2021). "It has been demonstrated that 4-OHE2 induces hypoxia-inducible factor-1 alpha (HIF-1) and vascular endothelial growth factor A (VEGF-A) expression in two human ovarian cancer cell lines, OVCAR-3 and A2780-CP70 cells, in dose- and time-dependent manners." (PMID 34462889, 2021). "In the present study, we did not explore the mechanism by which GRB7 regulates the expression and secretion of VEGFA in ovarian cancer cells." (PMID 34783299, 2021). "In vitro stimulation of human normal fibroblasts with LPA (as well as with conditioned medium from an ovarian cancer cell line) converted these cells into CAFs that expressed αSMA, TGFβ1, TGFβ2, VEGFA, VEGFB, FAP, CXCL12 and IL-6." (PMID 34200030, 2021). "Downregulation of VEGFA expression can inhibit the proliferation, angiogenesis and metastasis of osteosarcoma cells, ovarian cancer and lung squamous cell carcinoma." (PMID 34630524, 2021). "In ovarian cancer cells, sepiapterin abrogated the increase in migration and proliferation triggered by vascular endothelial growth factor-A (VEGF-A) and p70S6K-dependent VEGRF2 expression in a NO-independent mechanism." (PMID 34502450, 2021). "This amplification contains genes such as VEGFA, which promotes angiogenesis and has been observed to be expressed at higher levels in distant ovarian cancer metastases." (PMID 32188490, 2020). "In conclusion, circASH2L plays a critical role in regulating ovarian cancer cell tumorigenesis, angiogenesis, and lymphangiogenesis through the miR-665/VEGFA axis and, therefore, is a possible candidate target for ovarian cancer treatment." (PMID 33330483, 2020). "In this study, the qRT-PCR, western blot assays, bioinformatics analyses, and the dual-luciferase reporter assay showed that circASH2L competes with VEGFA for binding to miR-665, thereby playing an oncogenic role in ovarian cancer." (PMID 33330483, 2020). "Wang and his colleagues reported that the tumorigenicity and progression of ovarian cancer were promoted by circRhoC, which functions as a miR-302e sponge to positively regulate VEGFA." (PMID 33330483, 2020). "Some studies have shown that VEGFA promotes tumor cell proliferation and angiogenesis, and VEGFA is closely related to ovarian cancer." (PMID 33330483, 2020). "Regulating the miR-665/VEGFA axis as a ceRNA, circASH2L promotes cell proliferation, invasion, VEGFA-mediated angiogenesis, and lymphangiogenesis to play an oncogenic role in ovarian cancer." (PMID 33330483, 2020). "Previous studies found that VEGFA played a role in the pathophysiological process of ovarian cancer." (PMID 33330483, 2020). "Taken together, these results indicated that a tight regulatory network of the OC2/VEGFA/EGFL6 axis functioned downstream to miR-6086 in ovarian cancer." (PMID 32393810, 2020). "Next, our analysis identified that OC2 and EGFL6 were the direct targets of miR-6086 and we further demonstrated the relationship between miR-6086 and the OC2/VEGFA/EGFL6 axis in ovarian cancer." (PMID 32393810, 2020). "In ovarian cancer cells, the BRAF V600E mutation lead to an increased expression of CXCL8 and of vascular-endothelial-growth-factor A (VEGFA)." (PMID 31762942, 2019).